VIM (vimentin)
Diseases named in the same sentence as VIM in open-access papers (continued):
Sharing a sentence is not in itself a finding about the gene and the disease.
pulmonary fibrosis (continued). "In studies of radiation-induced pulmonary fibrosis, the radiation dose at 6 Gy significantly inhibited the expression of E-cadherin and promoted the expression of vimentin in AT2 cells." (PMID 36499337, 2022). "The expressions of α-SMA, N-cadherin, and vimentin can advance the development of IPF during the occurrence of pulmonary fibrosis." (PMID 36355019, 2022). "This latter finding is significant, as cit-vimentin has been shown to contribute to the activation of fibroblasts and development of experimental pulmonary fibrosis via a PAD2-dependent mechanism in IPF20." (PMID 35181688, 2022). "Another study also suggested the involvement of citrullinated vimentin derived from lung macrophages as a DAMP during the progression of lung fibrosis." (PMID 36429008, 2022). "For example, administration of citrullinated vimentin promotes pulmonary fibrosis through its action as a Toll-like receptor 4 ligand." (PMID 35717175, 2022). "The change of fibroblast shape and reduction of collagen deposition, α-SMA, and vimentin indicated that AOBEE had an obvious anti-pulmonary fibrosis effect by blocking the proliferation and migration of the activated fibroblasts." (PMID 33929970, 2021). "An intra-gastric administration of PRQ in mice elicits pulmonary fibrosis and promotes an up-regulation of vimentin, an EMT marker as well as a down-regulation of E-cadherin." (PMID 34658913, 2021). "In vivo, the effects of VPA on bleomycin-induced lung fibrosis were evaluated by assessing variables such as survival rate, body weight and histopathological changes, whilst the expression of E-cadherin and vimentin in lung tissue was also evaluated." (PMID 34168289, 2021). "We also assessed the expression levels of collagen 1α1, fibronectin, αSMA, and vimentin, which are the markers of the main effector cells of pulmonary fibrosis." (PMID 34168562, 2021). "Both VPA and A8301 improved E-cadherin and reduced vimentin expression in fibrotic lung tissue compared to mice with lung fibrosis (p < 0.05)." (PMID 34168289, 2021). "Previous research results have confirmed that EMT was a key step in the progression of pulmonary fibrosis, and the levels of vimentin was elevated in IPF samples while E-cadherin level was depressed." (PMID 32448163, 2020). "Current studies have established that PTL inhibit pulmonary fibrosis increasing E-Cadherin and decreasing vimentin NF-κB and Snail expression in TGF-β1-treated primary lung epithelial cells." (PMID 31417401, 2019). "To further investigate the antifibrotic action of sh-lnc-PCF in vivo, we tested the expression levels of E-cadherin, SP-C, α-SMA, collagen III, and vimentin, which are indicators of pulmonary fibrosis, after sh-lnc-PCF spraying in vivo." (PMID 29072702, 2017). "The lesions in MWCNT-instilled lungs displayed increased vimentin signal indicating increased fibroblast proliferation in these tissues, which is consistent with pulmonary fibrosis." (PMID 28903780, 2017). "In vimentin KO mice exposed to lipopolysaccharide, asbestos, or bleomycin, there are reduced levels of mature IL-1β and consequently, lung alveolar damage, inflammatory cell infiltration, and pulmonary fibrosis are diminished." (PMID 40251523, 2025). "After nuclear export, cytoplasmic lnc668 promoted the translation and stability of PICALM mRNA, leading to increased levels of differentiation-related and fibrotic proteins, such as FAP, α-SMA, COL1A, COL3A, and VIM, thus contributing to the progression of pulmonary fibrosis." (PMID 40221424, 2025). "Besides, a prior investigation has demonstrated that Entrectinib can suppress vimentin and N-cadherin expression in mice with bleomycin-induced pulmonary fibrosis." (PMID 39333897, 2024). "A number of studies suggest that polyubiquitination is s critical post-translational modification that mediates vimentin expression and stability.For example, PD-L1 can bind to vimentin to inhibit vimentin ubiquitination degradation, resulting in pulmonary fibrosis." (PMID 38383479, 2024).
pulmonary fibrosis (continued). "Furthermore, treatment with citrullinated vimentin mediates development and progression of lung fibrosis through Toll-Like Receptor 4 (TLR4)-dependent nuclear factor kappa-light-chain-enhancer of activated B cells (NF-κB) activation in mice." (PMID 38155185, 2023). "It has been shown that citrullination of cytoskeletal proteins has functional consequences on cell physiology; for example, the citrullination of collagen II affects integrin-mediated cell adhesion, and the citrullination of vimentin mediates the development and progression of lung fibrosis." (PMID 36401289, 2022). "Citrullinated vimentin mediates development and progression of lung fibrosis." (PMID 34634931, 2021). "Since PDGFRα + fibroblasts also contribute to collagen deposition in the bleomycin-induced pulmonary fibrosis model, we also performed double staining of PDGFRα and vimentin, and results showed that Fed treatment decreased the PDGFRα + fibroblasts compared with that in the BLM group." (PMID 34361644, 2021). "Targeting vimentin has been shown to be effective in reducing lung fibrosis." (PMID 34634931, 2021). "Immunofluorescence and western blot analyses revealed that BLM treatment decreased the levels of E-cadherin and increased the expression of vimentin in lung tissue, suggesting a decrease or variation in epithelial cells and an increase in interstitial cells during lung fibrosis." (PMID 28725012, 2017). "To further investigate the antifibrotic action of miR-30a agomir in vivo, we tested the expression levels of hydroxyproline (HYP), a smooth muscle actin (a-SMA), E-cadherin, and vimentin, which are indicators of pulmonary fibrosis, after miR-30a agomir spraying in vivo." (PMID 28294974, 2017). "However, after treatment with Sim, the expression of E-cad was remarkably increased while the expressions of α-SMA and Vimentin were significantly decreased, suggesting that Sim may alleviate pulmonary fibrosis by inhibiting the EMT process." (PMID 38720270, 2024). "Notably, we found that DEPs induced fibrosis-related changes, along with increases in the levels of collagen, β-catenin, vimentin, and TGF-β; these findings suggest the involvement of endogenous Wnt/β-catenin and YWHAZ-induced vimentin in pulmonary fibrosis pathways." (PMID 37888708, 2023). "And the result showed that in the BLM group, there were appropriately 18% Tie2+Vimentin+ (which is the fibroblast special marker) ECs, which offers strong evidence that the number of ECs decreased and transitioned into fibroblasts during the pathological progression of pulmonary fibrosis." (PMID 33771973, 2021). "Because both Pro-SPC and vimentin can act as the alveolar epithelial cells and pulmonary fibroblasts specific proteins, we therefore could evaluate the degree of pulmonary fibrosis by determining their amount of expression via immune-histochemical and immune-fluorescent methods." (PMID 30918525, 2019). "The authors demonstrate that vimentin-deficient mice are protected from asbestos- and bleomycin-induced lung injury and fibrosis and that vimentin-expressing bone-marrow-derived cells are important for bleomycin-induced activation of the NLRP3 inflammasome and pulmonary fibrosis." (PMID 27001429, 2016). "The vimentin immunization model of systemic sclerosis exhibited accelerated skin and lung fibrosis compared to the bleomycin (BLM)-induced model, along with increased activation of Th2 and Th17 cells and enhanced autoantibody production against vimentin." (PMID 41280911, 2025). "Consistent with our results regarding EMT, a pulmonary fibrosis study showed that treatment of MRC-5 and A549 cells with AXT led to upregulation of E-cadherin and downregulation of vimentin in vitro." (PMID 38555458, 2024). "Fibronectin, vimentin, and alpha-smooth muscle actin (α-SMA) are three important ECM proteins that play key roles in the pathogenesis of pulmonary fibrosis." (PMID 38750140, 2024).
pulmonary fibrosis (continued). "Vimentin promotes BLM- and PD-L1-induced fibrosis in Human Pulmonary Alveolar Epithelial Cells, thereby promoting lung fibrosis." (PMID 38263193, 2024). "To further assess the effect of heat exposure on lung fibrosis, we examined the expression of EMT-related genes (E-cadherin, Vimentin, α-SMA, CTGF, Snail1, Slug)." (PMID 38474239, 2024). "We also revealed mild Gucy1α1 expression in the normal human lung which was elevated in interstitial pulmonary fibrosis (IPF), colocalizing with αSma- and VIM." (PMID 39184103, 2024). "Our combined PCR array–omics analysis demonstrated that DEPs can induce airway inflammation and lead to lung fibrosis through changes in the expression levels of YWHAZ, β-catenin, vimentin, and TGF-β." (PMID 37888708, 2023). "Mechanistic analyses showed that the vimentin and TGF-β levels increased due to interactions among YWHAZ, β-catenin, vimentin, and TGF-β, all of which are involved in the induction of lung fibrosis." (PMID 37888708, 2023). "We also detected pulmonary interstitial fibrosis tendency by immunofluorescence staining of pro-fibrosis factors α-SMA and vimentin." (PMID 37218012, 2023). "Immunofluorescence staining showed that the expression levels of the fibroblast markers vimentin, α-SMA and collagen 1 in lung tissue were increased in the SiO2 group compared with the normal saline (NS) group, confirming the occurrence of pulmonary fibrosis." (PMID 35216634, 2022). "In the present study, we showed the upregulation of α-SMA and vimentin and the downregulation of VE-cadherin in in vitro and in vivo BLM-induced pulmonary fibrosis." (PMID 35897764, 2022). "Bleomycin-induced pulmonary fibrosis in mice exhibited that AOBEE improved forced vital capacity (FVC) and alveolar structure and inhibited α-SMA, vimentin, and collagen expression." (PMID 33929970, 2021). "In pulmonary fibrosis, high ITGBL1 expression increases the fibrotic markers, such as a‐SMA, vimentin and collagen, and promotes myofibroblast proliferation and migration, thus resulting in fibrogenesis." (PMID 33533071, 2021). "ATG reduced the expressions of Vimentin and α-SMA (lung fibrosis markers) induced by PQ and restored the expressions of E-cadherin and Occludin (two epithelial markers) in vivo and in vitro." (PMID 33390951, 2020). "And our experimental results indicated that imrecoxib can reduce the inhibition on E-cadherin and promotion on vimentin in paraquat-induced A549 cells and then inhibit the EMT activated by paraquat, so as to treat paraquat-induced pulmonary fibrosis." (PMID 33123215, 2020). "Recent single cell sequencing studies showed that epithelial shape changed and the expression of SNAI1, Vimentin and planar polarity genes increased, indicating a partial EMT-like phenotype in epithelial cells of pulmonary fibrosis patients." (PMID 33390951, 2020). "Unexpectedly, a much less severe lesion of pulmonary fibrosis was observed in Mutyh−/− than in Mutyh+/+mice, which was supported by assay on protein levels of TGF-β1 and both fibrotic markers, α-SMA and Vimentin, in pulmonary tissues of the model animals." (PMID 33149810, 2020). "Vimentin promotes ALI, alveolar epithelial barrier permeability and lung fibrosis by regulating NLRP3 inflammasome signaling." (PMID 29029603, 2017). "In epithelial-mesenchymal cell transition (EMT), which occurs in pulmonary fibrosis, is seen the concomitant increased amounts of mRNA levels of α-SMA, FSP1 and vimentin." (PMID 28288584, 2017). "Additionally, pulmonary fibrosis was induced by TGF-β-induced epithelial-mesenchymal transition (EMT), as indicated by reduced vimentin and preserved E-cadherin expression." (PMID 41727204, 2026). "Similarly, OMT alleviated CS-induced pulmonary fibrosis and EMT, as shown by decreased collagen deposition and normalization of EMT marker expression (E-cadherin, vimentin, and α-smooth muscle actin [α-SMA]) in lung tissues." (PMID 41147518, 2025).
pulmonary fibrosis (continued). "The cited study is not the only one in which pulmonary fibrosis was characterized by increased levels of α-smooth muscle actin, fibronectin, and vimentin (one or two of them) without assessment of other EMT markers." (PMID 40860870, 2025). "Deletion of the miR-301a gene in experimental mice led to reduced expression of vimentin, α-SMA, and fibronectin, thereby mitigating the severity of pulmonary fibrosis following BLM injection and suppressing the proliferation and activation of pulmonary fibroblasts." (PMID 39479511, 2024). "EMT is a process of pulmonary fibrosis during which alveolar epithelial cells lose their identity and transform into mesenchymal epithelial cells, accompanying by downregulated expression of E-cad and upregulated expressions of α-SMA and Vimentin." (PMID 38720270, 2024). "Vimentin, as an important stimulator of EMT, is also a key factor in lung fibrosis." (PMID 38263193, 2024). "The classical markers of EMT such as E-cadherin and vimentin, were assessed by immunohistochemistry to verify whether SIN was able to alleviate pulmonary fibrosis by inhibiting BLM-induced EMT." (PMID 38730387, 2024). "Furthermore, ELISA was used to detect pulmonary fibrosis markers COL-1, COL-3, WNT, Vimentin, β-Catenin, Fibronectin, α-SMA, N-Cadherin, E-Cadherin, TWIST, CTGF, FGF2, PDGF-α, MMP2, MMP8, MMP9, MMP13, TIMP1, TGF-β, Smad2, and Smad3 expression levels." (PMID 37812357, 2023). "Moreover, YVAD treatment significantly preserved VE-cadherin levels with decreased levels of vimentin and α-SMA in vascular endothelial cells after bleomycin-induced pulmonary fibrosis." (PMID 37958797, 2023). "Moreover, β-catenin induces vimentin, α-SMA, and collagen-I in A549 alveolar epithelial cells during pulmonary fibrosis." (PMID 36578010, 2022). "One study showed that in mouse models of IPF with only alveolar epithelial cells expressing β-gal, cells with increased vimentin were nearly always positive β-gal, suggesting that alveolar epithelial EMT is an important source of fibroblasts in pulmonary fibrosis." (PMID 36499337, 2022). "Mefunidone was shown to reduce the expression of Snail and vimentin by inhibiting the transduction of the TGF-β/Smad2 signaling pathway and the activation of the MAPK pathway, thereby inhibiting the process of EMT and improving pulmonary fibrosis." (PMID 36479180, 2022). "In the bleomycin-induced pulmonary fibrosis model, cytomegalovirus is considered to accelerate existing fibrosis according to enhancing TGFB1 activation and the expression of both phospho-SMAD2 and Vimentin." (PMID 34880861, 2021). "To investigate whether ATG improved the lung fibrosis by restraining EMT, we labeled Vimentin, α-SMA, E-cadherin and Cytokeratin 18 in paraffin sections of lung tissue by immunohistochemical staining." (PMID 33390951, 2020). "Moreover, an immunohistochemical study of human pulmonary fibrosis revealed that myofibroblasts express SMA, vimentin, and desmin." (PMID 32807166, 2020). "The miR-344a-5p mimic rescued the function of lnc-PCF in lung fibrosis and the expression of E-cadherin expression, which was inhibited by lnc-PCF overexpression, and reduced the expression of α-SMA, vimentin, and Snail, which were promoted by lnc-PCF overexpression." (PMID 29072702, 2017). "Without NLRP3 inflammasome signaling, bone marrow chimeric mice lacking vimentin have decreased lung fibrosis when induced by asbestosis." (PMID 29029603, 2017). "Our results showed that the TGF-β1-treated A549 cells exhibited downexpression of E-cadherin and overexpression of vimentin, suggesting that dys-regulation of AEC II contributes to the characteristic aberrant repair process and the pathogenesis of pulmonary fibrosis." (PMID 23967091, 2013).
pulmonary fibrosis (continued). "Importantly, the latest research in 2023 further clarifies their correlation, as heightened PDL1 levels impede vimentin ubiquitination, consequently amplifying vimentin levels and intensifying the EMT of alveolar epithelial cells, thus exacerbating pulmonary fibrosis." (PMID 37649487, 2023). "TGF-β has long been proposed as a key molecule in the pathogenesis of lung fibrosis, playing a pivotal role in that it stimulates intrapulmonary fibroblasts to express high levels of collagen genes and mesenchymal cell-related markers such as α-smooth muscle actin (α-SMA) and vimentin." (PMID 34944747, 2021). "Our data showed that iPS cell administration obviously up-regulated E-cadherin expression and down-regulated the expression of fibronectin, vimentin and α-SMA in lung tissues of BLM-stimulated mice, suggesting that iPS cells might suppress pulmonary fibrosis via inhibiting EMT." (PMID 27895584, 2016). "We feel that the co-localization of vimentin, pSMAD3 and COMP in fibrotic foci in human IPF lungs suggests that TGF-β1 induces COMP secretion mostly in fibrotic regions of IPF lungs and to some extent more informative than using a limited model of lung fibrosis." (PMID 24376648, 2013). "Since HGF-expressing, CXCR4+ cells in UIP did neither co-stain with vimentin nor with α-SMA, we assume that these cells are not fibrocytes that were recently described to play a major role in the pathogenesis of pulmonary fibrosis." (PMID 23840329, 2013). "Notably, a direct interaction between vimentin and NLRP3 was demonstrated as well as an important role for macrophages based upon the finding that bone marrow chimeric mice lacking vimentin have decreased lung fibrosis as well as levels of caspase-1 and IL-1β." (PMID 26370974, 2015).